FOXM1 (forkhead box M1)
Diseases named in the same sentence as FOXM1 in open-access papers (continued):
Sharing a sentence is not in itself a finding about the gene and the disease.
tumor (continued). "Overexpression of CDK1 mRNA and protein has been frequently observed in tumor tissues, potentially driven by gene amplification or activation of upstream transcriptional regulators such as E2F1 and FOXM1." (PMID 41009727, 2025). "Moreover, PIK3CA altered tumours that have been rendered resistant to PI3Kα inhibition through loss of PTEN show lack of FOXM1 downregulation, suggesting FOXM1 may play a role in limiting the efficacy of agents targeting the PI3K-AKT pathway." (PMID 40263319, 2025). "Histological analysis revealed increased tumour necrosis and reduced expression of forkhead box protein M1 (FOXM1), a transcription factor, further supporting the potential of BBR in limiting tumour progression." (PMID 41226384, 2025). "In a study on colon cancer, suppression of FOXM1 led to reduced PRDX3 expression in CD133+ CSCs, resulting in decreased tumor sphere formation and sensitization to chemotherapy." (PMID 40608151, 2025). "Further, RNA-seq of BT549 cells after siKNSTRN revealed pronounced downregulation of critical cell cycle-related genes, including CDK2, CDC20, FOXM1, and E2F1, which have been documented to drive uncontrolled proliferation and tumor growth in TNBC." (PMID 41209020, 2025). "Collectively, these studies provide evidence that FOXM1 is positioned downstream of the PI3K/AKT and JNK/P38 MAPK signaling pathways to facilitate tumor progression." (PMID 39781349, 2025). "In vivo and in vitro experiments reveal that the AKR1C1 inhibitor avasimibe inhibits OS cell proliferation and tumor growth by reducing the expression of AKR1C1 and FoxM1." (PMID 39964621, 2025). "Forkhead-box protein M1 (FOXM1), a proto-oncogenic transcription factor, plays a role in tumor growth, resistance to chemotherapy, and stem cell maintenance, and its expression is associated with worse patient outcome." (PMID 40725039, 2025). "Compared to wild-type cells, a homozygous Cr-Y575F cell line expressing endogenous FOXM1(Y575F) that was generated by CRISPR/Cas9 showed obviously delayed mitosis progression, impeded colony formation and inhibited xenotransplanted tumor growth." (PMID 39060421, 2024). "We validated FOXM1 for the first time as a critical therapeutic target in TNBC using genetic siRNA technology, resulting in significant inhibition of TNBC tumor xenografts in mice, suggesting that that FOXM1 represents an Achilles heel for targeting TNBC." (PMID 39594778, 2024). "To explore the expression level of FOXM1 in HCC, we conducted a comprehensive analysis using the TCGA database, evaluating FOXM1 expression in various tumour types." (PMID 38063438, 2024). "This study characterizes FOXM1 as a significant EAC-promoting TF and elucidates its novel function in regulating anti-tumor immune response." (PMID 38373993, 2024). "In tumor-bearing mice, SH3PXD2A-AS1 inhibition suppressed tumor growth and the protein levels of Ki67, SIRT7, and FOXM1." (PMID 39020302, 2024). "In summary, our paper elucidated that knocking down KIAA1429 can reduce FOXM1 expression through YTHDF1-mediated m6A modification, thereby inhibiting MM aerobic glycolysis and inhibiting tumor development." (PMID 39060874, 2024). "Overall, this study identifies the regulation of FOXM1 by microRNA-532-3p via its interaction with FOXM1 3’UTR, resulting in the suppression of proliferation, migration, and invasion, suggesting its role as a tumor suppressor in CRC." (PMID 39272919, 2024). "Studies have found that FOXA1, FOXM1, FOXO3, FOXP1, and so on play an important role in tumors as oncogenes or tumor suppressor genes." (PMID 38608123, 2024). "In line with above results, the WB analysis in tumor tissues of mice suggested that the protein levels of FOXM1 and E2F1 were significantly upregulated in CDCA5-overexpressiong tumor tissues." (PMID 38978058, 2024). "USP21 inhibitors are able to inhibit the deubiquitylation of MEK2 and FOXM1, which in turn down-regulates the expression of the ERK pathway and ultimately inhibits the growth of tumor cells." (PMID 39315102, 2024).
tumor (continued). "Inhibition of FOXM1 has been shown to reduce the expression of MMP-2 and MMP-9, and suppress the migration and invasion of tumor cells." (PMID 39594778, 2024). "The FOXM1 expression, the level of ABL1 phosphorylated at Y412 (pY412), and Ki67 level were significantly increased in tumor tissues compared to paracarcinoma tissues, indicating an essential role of ABL1 activation in FOXM1 expression and cell proliferation." (PMID 39060421, 2024). "In tumor-bearing mice, silencing of SH3PXD2A-AS1 suppressed tumor growth and the protein levels of Ki67, SIRT7, and FOXM1." (PMID 39020302, 2024). "FT282-C11 cells have low expression of FOXM1, FOXM1-P (activated FOXM1), CCNB1 (canonical FOXM1 target), FOXA1, and FOXK2 (all oncoproteins), and elevated FOXO3a (a tumor suppressor), as compared to HGSOC cells, validating their utility as a normal control." (PMID 38704607, 2024). "Tumor spots from the S2_Col_R and S4_Col_Sig patients showed lower EGFR signaling, while FOXM1 displayed higher transcriptional activity in patient S6_Rec." (PMID 38200223, 2024). "Inducing hypoxia‐mediated tumor proliferation, ALKBH5 downregulates m6A modifications on Forkhead box M1 (FOXM1) mRNA and enhances FOXM1 protein expression, consequently fostering LUAD progression." (PMID 38706740, 2024). "Consistent with tumor suppression, effectors of tumorigenesis (Myc, Myb, NKX2-3, and TRIM24), metastasis (NFE2L2), oncogenic transformation (FOXM1), and cell cycle (E2F2 and E2F3) were also inhibited in the presence of PRKN." (PMID 39213189, 2024). "Tumor initiation is a key defining property of CSC; we therefore tested the effect of FOXM1 ablation on the tumor-initiating ability of OC cells." (PMID 38806454, 2024). "miR-509-3p inhibited GC by regulating FOXM1-mediated p38/MK2 pathway activation, and miR-509-3p mimics restrained tumor growth in vivo through this pathway." (PMID 39319839, 2024). "To investigate the functional role of FOXM1 in EAC, we first established a patient-derived tumor organoid model using gastroesophageal organoid culture protocols established by us and others." (PMID 38373993, 2024). "The combined treatment of a PLK1 inhibitor (volasertib) and a FoxM1 inhibitor (thiostrepton) demonstrated a synergistic effect in reducing PTC cell growth in vitro and delaying tumor growth in vivo." (PMID 38361222, 2024). "Using short-hairpin RNA-mediated endogenous knockdown of FOXM1 in LLC tumor cells, we revealed that ablation of tumor-intrinsic FOXM1 attenuated the tumorigenesis capacity of LLC cells in vivo." (PMID 38577601, 2024). "We next evaluated the essential role of FOXM1 in CDCA5-induced tumor growth in vivo by subcutaneous injection of CDCA5-overexpressed, FOXM1-depleted, CDCA5-overexpressed + FOXM1-depleted or NC MDA-MB-231 cells." (PMID 38978058, 2024). "The high expression of mRNA in FOXA1 (P < .05), FOXM1 (P < .01), and FOXP1 (P < .05) groups was related to tumor stage." (PMID 38608123, 2024). "FOXM1-PROTAC mediated degradation of FOXM1 protein in tumor cells and suppressed viability, migration and invasion in several types of tumor cells." (PMID 36733484, 2023). "Thiazolidinedione (TZD) inhibits FOXM1 expression through the downregulation of SP1, negatively regulating tumor cell growth and promoting apoptosis." (PMID 36661515, 2023). "FOXA1, FOXM1, FOXO subfamily genes, and FOXR1 have been widely studied and confirmed to promote tumor progression through various pathways, such as proliferation, invasion, and immunity." (PMID 37563111, 2023).
tumor (continued). "By non-invasively predicting FOXM1 mRNA expression in HCC tissues using dual-region CT radiomics technology, clinicians can gain invaluable insights into the tumor’s molecular landscape even before surgical intervention." (PMID 37817774, 2023). "Using a proximity ligation assay (PLA), we detected interactions involving endogenous FOXM1 and activated SFKs phosphorylated on Y416 [p-SFK (Y416)] in c-Src–proficient tumor cells and premalignant mammary epithelial cells." (PMID 36795481, 2023). "On the one hand, elevated expression of FOXM1 promotes tumour cell proliferation and, on the other hand, FOXA1 inhibits tumour progression by suppression of PIK3R1 expression." (PMID 36688815, 2023). "We found that FOXM1, FOXP1, and FOXN3 were negatively correlated with OS and that FOXP1 and FOXN3 were positively correlated with histological grade and tumor size." (PMID 36622275, 2023). "As CEP55 is also transcriptionally regulated by the YAP/TEAD/FoxM1 complex, several molecular mechanisms cooperate in CEP55-dependent tumor cell dissemination." (PMID 37381005, 2023). "In line with our in vitro results, persistent high MAD2 levels resulted in decreased fitness and a delayed tumor onset while the combined overexpression of MAD2 and FOXM1 reverted this effect." (PMID 37452072, 2023). "To explore the phosphorylation and expression of FoxM1 in LUAD patients, we carried out immunohistochemistry on tissues from LUAD patients (Super Bio Chips, Korea), categorized by their tumor grade." (PMID 37968723, 2023). "Immunohistochemistry (IHC) staining for BTBD16, EpCAM, FOXM1, AGXT and JMJD1C was carried out in normal and tumor thyroid tissue samples (three patient biopsies available), belonging to two NMTC families: NMTC_1 and NMTC_4." (PMID 37175550, 2023). "Tumor cells with high levels of MAD2 can adapt over time by accumulating FOXM1, which renders them vulnerable to FOXM1 inhibition." (PMID 37452072, 2023). "Catalytically active PLK1, a kinase of FoxM1 in mitosis, drives the EMT and promotes tumor survival through activation of TGF-β signaling and PD-L1 expression." (PMID 37968723, 2023). "Unexpectedly, the correlation analysis between the upstream regulator's analysis identified MYBL2, E2F2, CBX3, FOXM1, and E2F1, which were significantly elevated in the LUAD or LIHC tumor groups, with a strongly correlated value with utility as biomarkers." (PMID 35404841, 2022). "As transcription factors, FOXM1 can regulate downstream cell cycle-related genes, including PLK, cyclin B1, cyclin D1, and Cdk2, to promote cell proliferation and tumor progression." (PMID 36585925, 2022). "The expression of CA9 was predominantly found in perinecrotic tumor cells, but the positive expression of HIF-1α, nestin, and FOXM1 was widely distributed." (PMID 35785200, 2022). "FOXM1 stimulates indoleamine 2,3 dioxygenase (IDO2) which stimulates T-reg cells which are immunosuppressive and induce tumour tolerance." (PMID 35354487, 2022). "By taking the intersection of the two cohorts, we identified 26 upregulated TFs with twofold upregulation in tumour tissues compared with NT liver tissues, although four of them (E2F1, FOXM1, LIN28B, and MYCN) were excluded for overrepresentation." (PMID 36008383, 2022). "The FOXO3/FOXM1 axis is an essential downstream signal of the PI3K/AKT, Ras/ERK, and JNK/p38MAPK pathways, which are also involved in the tumor growth mediated by controlling the cell cycle." (PMID 36619388, 2022). "The statistical analysis of tumor size data revealed that the tumor volume of the FOXM1-PROTAC experimental group was much smaller than that of the control group, indicating that FOXM1-PROTAC had a significant inhibitory effect on tumor growth." (PMID 36171633, 2022).
tumor (continued). "Gene expression profiles of the high-risk group correlated positively with the upregulation of CSC markers, CD24, CD44, CD20, FOXM1, and EpCAM, and significant enrichment of other ESC signatures, indicating that these were tumor-promoting targets." (PMID 35814473, 2022). "In HCC cells, FOXM1 increases the expression of VEGF, which is required for angiogenesis, and contributes to the acquisition of an aggressive tumor phenotype." (PMID 35053606, 2022). "MiRNA-370, as a tumour suppressor, is downregulated due to aberrant CpG island methylation in AML, which subsequently results in the upregulation of FOXM1, a tumour-promoting factor." (PMID 35838271, 2022). "To validate the relationship between cytokine levels and FOXM1 expression, we treated cells with recombinant human TGF‐β1, a well‐known cytokine predominantly released from the tumour microenvironment." (PMID 35656815, 2022). "In the present study, we found that tumour microenvironment factors can induce the stabilization of HIF‐1α and increase the expression of FOXM1 in NPC cells under hypoxic and normoxic conditions." (PMID 35656815, 2022). "circ-PTK2 affects the miR-330-5p/forkhead box M1(FOXM1) axis by binding to miR-330-5p, accelerating tumor progression, and inhibiting tumor apoptosis." (PMID 35795049, 2022). "In the present study, “pseudo-papillary” structures containing nestin+/FOXM1+ cells in the perivascular niche and CA9/HIF-1α positivity in the area surrounding stem cell accumulation resembled co-opted tumor vessels and were observed in refractory-Bev." (PMID 35785200, 2022). "Then Western blotting was used to test the protein expression levels of FOXM1, Cyclin B1 and CENPF in tumour tissues, the results showed that the protein expression were inhibited by SH3PXD2A-AS1 knockdown." (PMID 35410446, 2022). "The increased VEGFA is secreted extracellularly via exosomes, an event potentiated by the interaction of FOXM1 with VPS11, eventually promoting tumor angiogenesis." (PMID 33314660, 2021). "To extend our findings into antimitotic chemotherapy response, we investigated the FOXM1-dependent co-regulation of BMF and BUB1B expression in the context of tumor cell treatment." (PMID 34035233, 2021). "Univariate analysis of gene expression data on tumor aggressiveness (NMIBC versus MIBC) using logistic regression showed genes, including CDKN2A, CTSV, FOXM1, and KRT23, were predictive of tumor aggressiveness." (PMID 34885040, 2021). "At the same time, FoxM1 is closely related to the expression levels of stem cell markers such as Nanog, Sox2 and OCT4 in tumor samples, and promoted the expression of these stem-related genes in vitro." (PMID 33588867, 2021). "Consistently, the results of our study revealed that FOXM1 could upregulate the expression of Linc-ROR in HNSCC cells, while the knockdown of Linc-ROR was shown to normalize the stimulatory effect associated with FOXM1 on tumor growth in the xenograft model of HNSCC cells." (PMID 34447693, 2021). "But there is a significant positive correlation of FoxM1 and STMN1 in most of the tested tumor cell lines." (PMID 33526768, 2021). "The results of univariate analysis demonstrate that CDKN2A, CTSV, FOXM1 and KRT23 were predictive of tumor aggressiveness (MIBC) and the odds of having MIBC was increased by 3% per unit increase of CDKN2Aa (p = 0.01)." (PMID 34885040, 2021). "Compared to that in the control group, the tumor size of the NOX4 + NTC group was significantly larger, but this effect was markedly abrogated by FOXM1 knockdown (NOX4 + shFOXM1 group)." (PMID 34740322, 2021). "I-BET151 was reported to impair tumor growth by displacing BRD4 from the chromatin, which reduced the expression of the Forkhead box protein M1 (FoxM1) transcription factor." (PMID 34758842, 2021). "The oncogenic functions of FOXM1 in HGSC include cell cycle progression, genomic instability, tumor invasion, and metastatic spread." (PMID 33890574, 2021).
tumor (continued). "Another connection between FOXM1 and LIN28 is that FOXM1 also regulates LINC01094, which acts as a miRNA sponge for MIR-577, a well-characterized tumor suppressor that controls LIN28, as well as b-catenin/wnt signaling and EMT." (PMID 34948433, 2021). "To further elucidate the mechanism of Linc-ROR regulating cell growth in HNSCC in vivo, we downregulated Linc-ROR and upregulated FOXM1 in TSCCA cells, and examined tumor growth by subcutaneous tumor formation assay." (PMID 34447693, 2021). "Stabilization of FOXM1 via deubiquitination by OTUB1 promotes cell proliferation and invasion of SKOV3 cells in vitro and increased tumor growth of SKOV3 mouse xenografts in vivo." (PMID 34205406, 2021). "In conclusion, we demonstrate that ALKBH5, which is positively regulated by epigenetic modifications of H3K27 acetylation, promotes tumor progression by inducing tumor EMT and increasing FOXM1 expression via m6A demethylation." (PMID 33428593, 2021). "We further identified CBP as a binding partner of SATB2 in activating FOXM1 expression to promote GSC proliferation and GBM tumor growth." (PMID 33124191, 2020). "Our results showed that knockdown of FOXM1 decreased active GTP-loaded state of Rho (GTP-Rho and GTP-Rac1) in RCC, therefore inactivating ECT2-Rho signaling to suppress tumor growth." (PMID 32257108, 2020). "Immunohistochemistry analysis demonstrated that protein levels of FOXM1 and Ki-67, a proliferation marker, were down-regulated with FAM188B knockdown in the tumor tissue." (PMID 33142744, 2020). "Higher levels of both FOXM1 and TPX2 correlated positively with larger tumors, poorer histological grade and later tumor-node-metastasis (TNM) stage." (PMID 32723329, 2020). "In this study, we test the effectiveness of a novel class of 1,1-diarylethylene FOXM1 inhibitory compounds in suppressing TNBC cell migration, invasion, and metastasis using in vitro cell culture and in vivo tumor models." (PMID 32961773, 2020). "Subsequently, qRT-PCR results showed that, compared with the non-tumor tissues, NNT-AS1 and FOXM1 were up-regulated, while miR-22 was down-regulated in LUSC tissues." (PMID 32514270, 2020). "FOXM1 and FOXO3A are two members of this family that are essential components of oncogenic and tumor-suppressive pathways, respectively." (PMID 32967092, 2020). "Here, we have now tested the ability of FOXM1 inhibitory compounds to suppress TNBC progression and tumor metastasis." (PMID 32961773, 2020). "Using mRNA expression data from 20 primary tumor samples, we found that the mRNA expression levels of DNMT1, FOXM1, and SOX2 were significantly increased in tumor tissues." (PMID 31296961, 2020). "Mechanistically, TRPM2-AS serves as a microRNA sponge or a competitive endogenous RNA (ceRNA) for tumor suppressive microRNA miR-612 and consequently modulates the derepression of IGF2BP1 and FOXM1." (PMID 32123162, 2020). "Bioinformatics analysis indicated that FOXM1+PLAU+ associated genes are enriched in TGF-beta, DNA repair and drug resistance signaling pathways; FOXM1 and PLAU expression are negatively correlated with tumor immune infiltration." (PMID 31949481, 2020). "As a transcription factor, FOXM1 crosstalk with multiple proteins including PLK1, Cyclin B1 and Aurora B, and thus plays a central role in tumor aggressiveness." (PMID 32047721, 2020). "We examined the gene expression levels of FOXM1 and FANCD2 in primary and recurrent tumor tissues in the NMIBC patient group." (PMID 32486251, 2020). "Next, we determined the levels of circ-FOXM1, miR-143-3p, FLOT2 mRNA, and FLOT2 protein in the collected tumor samples." (PMID 32183822, 2020). "FOXM1-SMAD interaction occurs downstream of the TGFβ signaling pathway and promotes tumor progression." (PMID 33680951, 2020). "We tested the ability of three FOXM1 inhibitory compounds (NB-73, NB-115, and NB-55) to suppress TNBC progression and tumor metastasis." (PMID 32961773, 2020).